HOXB-AS4 (HOXB cluster antisense RNA 4)
Gene: Long non-coding RNA gene on chromosome 17 (48,628,675 to 48,634,932, forward strand). Ensembl gene ENSG00000242207.
Diseases named in the same sentence as HOXB-AS4 in open-access papers:
HOXB-AS4 is named in the same sentence as 3 diseases in open-access papers, as found by Europe PMC text mining. Sharing a sentence is not in itself a finding about the gene and the disease. The quoted sentences say what the papers report.
pancreatic cancer (2 papers, 2020 to 2021). "Genome-wide screening isolated HOXB-AS4 as specifically methylated in pancreatic cancer cells, which was useful to assess a cancer cell fraction in DNA samples." (PMID 32174965, 2020). "Genome-wide screening found HOXB-AS4 as specifically methylated in pancreatic cancer cells." (PMID 33517850, 2021).
cancer (2 papers, 2020 to 2022). A tumor composed of atypical neoplastic, often pleomorphic cells that invade other tissues. "Little is known about prognostic effects of AL590094.1 and HOXB-AS4 on the prognosis of cancer." (PMID 35350243, 2022).
HOXB-AS4 also shares sentences with these, for which no sentence is quoted: tumor (1 paper).